PHF12 (PHD finger protein 12)
Description:
Transcriptional repressor acting as key scaffolding subunit of SIN3 complexes which contributes to complex assembly by contacting each core subunit domain, stabilizes the complex and constitutes the substrate receptor by recruiting the H3 histone tail. SIN3 complexes are composed of a SIN3 scaffold subunit, one catalytic core (HDAC1 or HDAC2) and 2 chromatin targeting modules. SIN3B complex represses transcription and counteracts the histone acetyltransferase activity of EP300 through the recognition H3K27ac marks by PHF12 and the activity of the histone deacetylase HDAC2. SIN3B complex is recruited downstream of the constitutively active genes transcriptional start sites through interaction with histones and mitigates histone acetylation and RNA polymerase II progression within transcribed regions contributing to the regulation of transcription. May also repress transcription in a SIN3A-independent manner through recruitment of functional TLE5 complexes to DNA. May also play a role in ribosomal biogenesis (By similarity).
Synonyms: Pf1; KIAA1523
Tractability: Small molecule: a structure with a bound ligand is known. PROTAC: UniProt records ubiquitination sites on it; ubiquitination databases record sites on it; its protein half-life has been measured.
Gene: Protein-coding gene on chromosome 17 (28,905,250 to 28,951,771, reverse strand). Ensembl gene ENSG00000109118.
Subcellular location: Nucleus
Subcellular location (Human Protein Atlas): Nucleoplasm
Gene Ontology:
Molecular function: phosphatidylinositol binding; protein binding; transcription corepressor activity; transcription corepressor binding
Biological process: negative regulation of DNA-templated transcription; negative regulation of transcription by RNA polymerase II
Cellular component: nucleoplasm; nucleus; Sin3-type complex; transcription repressor complex
Genetic constraint (gnomAD): Loss-of-function variants: 6 observed, 103.34 expected, observed/expected ratio (o/e) 0.0581, 90% interval 0.031 to 0.12. The upper end of that interval is the gene's LOEUF score, 0.12, which puts it in group 1 of 6, group 1 being the genes least tolerant of losing a copy. Missense variants: 954 observed, 1,366 expected, observed/expected ratio (o/e) 0.7, 90% interval 0.66 to 0.74. Synonymous variants: 480 observed, 542.4 expected, observed/expected ratio (o/e) 0.88, 90% interval 0.82 to 0.95.
Gene-disease validity (ClinGen):
ClinGen rates the evidence that PHF12 causes each of these diseases.
complex neurodevelopmental disorder (autosomal dominant): Definitive. A disorder that involves more than one phenotype associated with the central nervous system, including but not limited to intellectual disability, autism, and seizures (epilepsy).
Homologues: Orthologues: chimpanzee PHF12 (99% identical), rabbit PHF12 (98% identical), dog PHF12 (98% identical), pig PHF12 (98% identical), macaque PHF12 (97% identical), mouse Phf12 (96% identical), rat Phf12 (96% identical), guinea pig PHF12 (84% identical), tropical clawed frog phf12 (68% identical), zebrafish phf12b (52% identical), zebrafish phf12a (51% identical), Drosophila melanogaster CG3815 (26% identical). Paralogues in human: ZMYND8 (17% identical), PHF21A (8% identical), ZMYND11 (8% identical), AIRE (6% identical), PHF21B (6% identical).
Diseases named in the same sentence as PHF12 in open-access papers:
PHF12 is named in the same sentence as 18 diseases in open-access papers, as found by Europe PMC text mining. Sharing a sentence is not in itself a finding about the gene and the disease. The quoted sentences say what the papers report.
breast carcinoma (2 papers, 2015 to 2019). "Here, we report the identification of the SID-containing adaptor protein PF1 (PHF12), which is expressed from a locus amplified in breast cancer, as a factor required for EMT and cancer stem cell maintenance in TNBC." (PMID 26460951, 2015). "We focused our investigation on the plant homeodomain (PHD)-containing protein PF1 (PHF12), which links SIN3 PAH2 to a chromatin-modifying protein complex containing MRG15, LID (the Drosophila homolog of KDM5A/B) and EMSY that has been implicated in breast cancer." (PMID 26460951, 2015).
triple-negative breast carcinoma (2 papers, 2015 to 2024). An invasive breast carcinoma which is negative for expression of estrogen receptor (ER), progesterone receptor (PR), and human epidermal growth factor receptor 2 (HER2). "Until now, there is still little research on the role of PHF12 in tumors, and previous study has found that disrupting the interaction between PHF12 and Sin3A complex can inhibit the migration and aggressiveness of triple negative breast cancer cells." (PMID 39075515, 2024).
lung adenocarcinoma (1 paper, 2024). A carcinoma that arises from the lung and is characterized by the presence of malignant glandular epithelial cells. "We detected PHF12 expression in GSE75037 dataset and TCGA database and found that PHF12 is upregulated in lung adenocarcinoma samples compared with adjacent normal tissue." (PMID 39075515, 2024).
lung carcinoma (1 paper, 2024). "We harnessed clinical lung cancer tissue samples and non-small cell lung cancer cell lines to discern the expression pattern of PHF12." (PMID 39075515, 2024). "Our study embarked on the elucidation of this ambiguity, unveiling that PHF12 collaboratively engages with HDAC1 to propel the proliferation of lung cancer cells." (PMID 39075515, 2024). "TCGA database also showed that PHF12 is significantly up regulated in lung cancer tissue compared with normal tissue." (PMID 39075515, 2024). "We also performed GSEA analysis to further explore the mechanisms of PHF12 in lung cancer development, and the results also showed that PHF12 was related to EGFR/ErbB2 signaling pathway." (PMID 39075515, 2024). "Despite this, the precise function of PHF12 in the intricate landscape of lung cancer development remained enigmatic." (PMID 39075515, 2024). "Our study identified PHF12 as an oncogenic role in lung cancer proliferation and migration for the first time." (PMID 39075515, 2024). "To investigate the function of PHF12 in lung cancer cell lines, we knocked down PHF12 expression in high PHF12-expressing cell lines A549, H1299, and H292, while overexpressing PHF12 in low PHF12-expressing cell lines including PC9 and H1975." (PMID 39075515, 2024). "ChIP-seq was performed using H292 cells to find out the role of PHF12 in lung cancer progression as a transcription factor." (PMID 39075515, 2024). "We performed RNA-seq analysis on control cells and PHF12 knockdown cells to explore the signaling pathway that PHF12 may regulate in the proliferation and metastasis of lung cancer." (PMID 39075515, 2024). "PHF12 may serve as an important target in lung cancer therapy." (PMID 39075515, 2024). "In our study, we confirmed for the first time the promoter role of PHF12 in non-small cell lung cancer and proposed that PHF12-HDAC1 axis regulates the EGFR/AKT signaling pathway and promotes the development of lung cancer." (PMID 39075515, 2024).
neuroblastoma (1 paper, 2025). Neuroblastoma (NB) is the most common solid, extracranial childhood tumor. "However, the information on ARID4B and PHF12 in cancer, particularly in neuroblastoma, was scarce." (PMID 40962798, 2025).
non-small cell lung carcinoma (1 paper, 2024). A group of at least three distinct histological types of lung cancer, including non-small cell squamous cell carcinoma, adenocarcinoma, and large cell carcinoma. "Within the scope of our investigation, a substantial upregulation of PHF12 was discerned in non-small cell lung cancer (NSCLC) tumor specimens, displaying a noteworthy correlation with a less favorable clinical prognosis." (PMID 39075515, 2024). "Our study has first revealed that PHF12 interacts with HDAC1 to regulate EGFR/AKT signaling pathway and promote proliferation in non-small cell lung cancer." (PMID 39075515, 2024).
cancer (4 papers, 2015 to 2025). A tumor composed of atypical neoplastic, often pleomorphic cells that invade other tissues. "After looking through the ChIP-seq results, we found that the most frequent binding peak sites of PHF12 in cancer cells were the intron region, accounting for 45.26%." (PMID 39075515, 2024). "The results showed that PHF12 is highly related to histone deacetylation in cancer cells." (PMID 39075515, 2024).
tumor (4 papers, 2015 to 2024). "On the contrary, tumor weight and tumor size of group with PHF12 stable overexpression were significantly increased compared to control group." (PMID 39075515, 2024). "Two subcutaneous tumor transplantation models were used to confirm the impact of PHF12 in tumorigenesis in vivo." (PMID 39075515, 2024). "Tumor weight and tumor size of PHF12 knockdown group were significantly declined compared to control groups." (PMID 39075515, 2024). "Notably, PHF12 exhibited a substantial upregulation within tumor tissue, concomitant with its correlation to HDAC1." (PMID 39075515, 2024).
PHF12 also shares sentences with these, for which no sentence is quoted: infection (3 papers); asthma (1); autism (1); B-cell lymphomas (1); coagulopathy (1); COVID-19 (1); depression (1); neurodevelopmental disorder (1); small cell lung carcinoma (1); Stroke (1).